ATF3 (activating transcription factor 3)
Diseases named in the same sentence as ATF3 in open-access papers (continued):
Sharing a sentence is not in itself a finding about the gene and the disease.
synovial sarcoma (1 paper, 2016). "In agreement with this, we see that treatment with tazemetostat does lead to an increase in ATF3 expression in the SS18-SSX positive but not negative synovial sarcoma cell lines." (PMID 27391784, 2016). "Thus, EZH2 inhibition does not change SOX2 expression in SS18-SSX positive synovial sarcoma cell lines, but is able to reverse some synovial sarcoma-specific gene expression, at least ATF3, and others less consistently across models." (PMID 27391784, 2016).
systemic sclerosis (1 paper, 2022). A chronic disorder, possibly autoimmune, marked by excessive production of collagen which results in hardening and thickening of body tissues. "Furthermore, ATF3 plays a profibrotic role in systemic sclerosis and bleomycin-induced lung injury." (PMID 36481938, 2022).
testicular germ cell tumor (1 paper, 2021). A germ cell tumor arising from the testis. "Similar to our findings, ARID1A downregulation in testicular germ cell tumors also leads to ATF3 upregulation." (PMID 34941867, 2021).
triple-negative breast carcinoma (1 paper, 2020). An invasive breast carcinoma which is negative for expression of estrogen receptor (ER), progesterone receptor (PR), and human epidermal growth factor receptor 2 (HER2). "For example, LYN-1604, as a novel activator of ULK1, obviously up-regulated ATF3 to induce autophagy in triple negative breast cancer." (PMID 32398095, 2020).
tuberous sclerosis complex (1 paper, 2018). "Another study reported that stress-induced ATF3–Gelsolin cascade is responsible for spine deficits in the tuberous sclerosis complex." (PMID 29515366, 2018). "Knocking down ATF3 expression with shRNA decreased Gelsolin expression and increased dendritic spine density in neuronal models of tuberous sclerosis complex." (PMID 29515366, 2018).
Uterine leiomyoma (1 paper, 2019). The presence of a leiomyoma of the uterus. "Early growth response gene 1 (Egr1) promotes the expression of AP-1; the induction of Egr1 in uterine leiomyoma cells led to a significant increase in the expression levels of Egr1, ATF3, Fos, and Jun." (PMID 31010998, 2019).
tumor (304 papers, 2007 to 2026). "Among the TFs associated with LTRs, ATF3 has been reported in the context of immune regulation, in particular for regulating NF- κB expression, cytokine production, and anti-tumor activities of T cells." (PMID 40989699, 2025). "Consistent with our earlier data, loss of ATF3 in DCs suppressed whereas ablation of CH25H stimulated tumor growth." (PMID 36333297, 2022). "Overexpression of ATF3 noted in NSCLC24 was associated with accelerated tumor progression and poor prognosis." (PMID 36333297, 2022). "This inhibition of LLC tumor growth in mice, whose DCs were deficient in ATF3, was further recapitulated in the subcutaneous tumor settings." (PMID 36333297, 2022). "The top motif enriched in upregulated peaks involved many transcription factors associated with tumor metastasis, such as AP-1 family members Fra1, JunB, Atf3, and Fos." (PMID 36579891, 2022). "Conversely, we demonstrate that tumor microenvironment-associated factors activate ATF3 and downregulate CH25H and its product 25HC thereby alleviating the negative regulation of the lysosomal activity." (PMID 36333297, 2022). "As several studies reported that ATF3 was significantly associated with tumor metastasis, the effect of ATF3 on GC cell migratory and invasive capabilities was further investigated by performing transwell assays." (PMID 34728784, 2021). "To test if the higher levels of ATF3 and the impaired tumor phenotype upon loss of USP22 in HER2+-BC are caused by sustained activation of the UPR, we analyzed several known markers and genes regulated by this pathway." (PMID 34007022, 2021). "Cancer-associated fibroblasts overexpressing ATF3 demonstrate rapid proliferation, as indicated by their enhanced colony-forming ability and fast growth in adjacent tumor cells, when co-injected into nude mice." (PMID 32922364, 2020). "In this study, we identify Atf3 as a novel polarity response gene induced by aPKC signaling upon loss of the neoplastic tumor suppressors of the Scrib polarity module." (PMID 29494583, 2018). "Here we demonstrate that Atf3 levels remain low as long as epithelial polarity is intact, whereas loss of polarity due to deficiency in tumor suppressors of the Scrib complex triggers Atf3 expression." (PMID 29494583, 2018). "Critically, we demonstrate that ATF3, with its target genes, is required for an invasion tumor cell phenotype and is robustly linked with poor prognosis in CRC." (PMID 28402947, 2017). "Various genes specifically expressed in BMDCs have been associated with tumor aggressiveness such as Ets2, Vegf, Hif1α, and Atf-3." (PMID 26497998, 2015). "Since CTNNB1 is a key downstream mediator in the Wnt signaling pathway, and an increase in active CTNNB1 has been linked to tumor proliferation and metastasis, we next investigated the role of SUMOylation on ATF3-mediated CTNNB1 expression." (PMID 23591848, 2013). "The SNAI1 and SNAI2 genes have been implicated in tumor progression and metastasis, and both were recently shown to be direct transcriptional target of ATF3 in human mammary cells." (PMID 21304988, 2011). "Depending on the cell type and the type and severity of the cell stressor, ATF3 has been implicated as both a proto-oncogene and tumour suppressor." (PMID 20828393, 2010). "ATF3 has been implicated in tumor promotion, metastasis, and reduced patient survival." (PMID 38658567, 2024). "In addition, the tumor-associated gene Activating Transcription Factor 3 (ATF3) was upregulated, and the oncogene Aldehyde Dehydrogenase 2 (ALDH2) was downregulated as the trajectory progressed." (PMID 37745301, 2023). "Accumulating evidence has shown that ATF3 is associated with tumor progression." (PMID 33816467, 2021).
tumor (continued). "Moreover, low ATF3 expression was significantly associated with clinical cancer stage and pathological tumor grade in patients with HCC." (PMID 33407456, 2021). "In addition, it was found that ATF3 expression potentially contributes to the regulation of tumor-associated and M1/M2 macrophages." (PMID 33407456, 2021). "Moreover, the gain- and loss-function experiments further verified the tumor promoting effect of ATF3 in PC that is critical for oncogenic function of MTA2TR." (PMID 31410216, 2019). "As another candidate metastasis-associated signaling factor in association with NAG-1 expression, activating transcription factor 3 (ATF3) can enhance tumor progression by inducing genes involved in tumor metastasis, which is advantageous for malignant cancer cells." (PMID 27708225, 2016). "As described in the results section, promoter analysis supported stronger regulation of cell cycle and of lipid metabolism in the tumor state by associating motifs of Atf3, Jun, E2f3, and Pparg with corresponding tumor genes and thus supported our previous findings." (PMID 21464922, 2011). "Therefore, we speculate that the epigenetic suppression of ATF3 might be essential for survival as tumors are exposed to increasing cellular and environmental stresses associated with tumor development, progression, and metastasis." (PMID 37104245, 2023). "Furthermore, Maf, Atf3, and Hif1a are potential regulators of regulatory myeloid (Mreg) cells, while Hif1a is a potential regulator of tumor-associated macrophages in MCA205 mouse tumors; these two myeloid subpopulations share the expression of Arg1 and Trem2 (Arg1+Trem2+)." (PMID 35359989, 2022). "It was reported that ATF3 could predict whether tumors were sensitive to histone deacetylase inhibitors, and ATF3 played an important role in the apoptosis of tumor cells caused by histone deacetylase inhibitors through transcriptionally inhibiting pro-survival factor BCL-XL4." (PMID 34480024, 2021). "However, ATF3 may also act as a tumor suppressor by inhibiting ARs, MMP2, and AKT, thereby causing inhibition of cell proliferation and invasion." (PMID 32922364, 2020). "Mechanistically, DSF/Cu synergistically increased the expression of activating transcription factor 3 (ATF3), a known tumor suppressor, in HCC cells." (PMID 41438581, 2026). "Ginsenoside Rh4 induces ferroptosis by inhibiting the KEAP1/NRF2/HO-1 pathway and remodeling the gut microbiota to increase butyrate levels, which synergistically enhance tumor cell ferroptosis sensitivity through ATF3 activation and suppression of GPX4." (PMID 41898564, 2026). "ATF3 is also expressed at low levels in multiple HCC tumor tissues and is significantly associated with clinical cancer stage and pathological tumor grade." (PMID 40361912, 2025). "Similar to TGFβ signaling, ATF3’s role and regulation of target genes likely changes following tumour initiation, growth, and metastasis." (PMID 41198649, 2025). "ATF3 directly inhibits AR transcriptional activity and downstream targets (e.g., PSA), while NR2F1 loss promotes tumor heterogeneity and enzalutamide resistance." (PMID 40470696, 2025). "ATF3 restricts tumour growth at the primary tumour site but promoted establishment of cancer cells at metastatic sites." (PMID 41198649, 2025).
tumor (continued). "Tumor factors can also activate the transcription factor Activating Transcription Factor 3 (ATF3), which suppresses the expression of cholesterol 25-hydroxylase (CH25H), thereby disrupting antigen processing and weakening cross-presentation." (PMID 41050070, 2025). "Mechanistically, we demonstrated that FADS1 plays a reciprocal role in ER stress and downregulation results in inhibition of tumor growth through induction of PERK/eIF2α/ATF4/ATF3-mediated ER stress response." (PMID 40121894, 2025). "For example, ATF3 has been shown to directly enhance PD-L1 transcription in tumor cells, which correlates with programmed cell death protein 1 (PD-1) blockade therapy efficacy." (PMID 41502516, 2025). "Through functional assays conducted in both ATF3-overexpressing (ATF3-oe) and ATF3-knockdown (ATF3-kd) cell lines, we verified the tumor suppressor role of ATF3 in HCC development." (PMID 39996726, 2025). "Western blot analysis confirmed efficient knockdown of ATF3 and IL-24 in tumor cells prior to implantation." (PMID 40866941, 2025). "Tumor-like fibroblasts exhibited elevated expression of stress-related genes ATF3 and JUN, which were enriched in the stress response and proliferation pathways." (PMID 40520021, 2025). "For sample P4.2, STModule identifies signal of inflammation (I; AQP3) and spatial expression of ATF3 (II), which plays an important role in regulating immune responses and exhibits dual functions as an oncogene or tumor suppressor." (PMID 40033360, 2025). "ATF3 exerts anti-tumour effects in gastric cancer and tongue squamous cell carcinoma by restricting Nrf2/Keap1 signaling or interferon-stimulating genes, respectively." (PMID 41198649, 2025). "In our investigation, we examined the expression of genes connected to stemness in the different tumor cell subtypes and determined that the expression levels of ATF3, CXCL2, RRAD, AREG, and CXCL8 were significantly higher in the C0 subtype." (PMID 40936936, 2025). "CDCA8 knockdown inhibits HCC development and stemness by inactivating oncogenic AKT/β‐catenin signaling and reinstating the ATF3 tumor suppressor." (PMID 39764737, 2025). "Since ATF3 expression was very low in both APA tumor and adjacent tissues from the spatial transcriptome analysis, we selected EGR1 for further investigation." (PMID 39826326, 2025). "In terms of mechanistic insights, classical oncology literature posits that tumor cells can upregulate the expression of PD-L1 through transcription factors such as ATF3, thereby exhausting effector T-cell function and achieving immune evasion." (PMID 41294838, 2025). "Tumor growth was monitored, revealing a significant increase in both tumor volume and weight in the experimental group compared to controls, suggesting that ATF3 knockdown promotes tumor growth in HCC, consistent with our in vitro results." (PMID 39996726, 2025). "We identified differences in the degree of neoplasia when ATF3 was targeted globally (APK) or specifically in acinar cells (AacinarPK)." (PMID 41198649, 2025). "Upon Vin treatment, control tumors exhibited significant growth inhibition, whereas tumors with ATF3 or IL-24 knockdown showed markedly reduced sensitivity to Vin, with minimal suppression of tumor growth observed." (PMID 40866941, 2025). "Overall, these results corroborate the tumor-suppressive role of ATF3, implying that HCC patients with high ATF3 expression levels have a more favorable prognosis." (PMID 39996726, 2025). "Given the differences observed between APK and AacinarPK mice in this study, further work is required to identify cell-specific roles for ATF3 in the developing tumour microenvironment during PDAC initiation and progression." (PMID 41198649, 2025). "In HSCs, ATF3 is activated by tumor-primed bone marrow MSCs, redirecting hematopoiesis toward monocytic cell expansion." (PMID 40730548, 2025).
tumor (continued). "They found that ATF3, a stress-responsive transcription factor, is upregulated in cytotoxic T lymphocytes (CTLs) exposed to tumor-derived signals." (PMID 41019052, 2025). "To further corroborate the tumor-suppressive role of ATF3 in HCC, we employed an ATF3 short hairpin RNA (shRNA) oligo to knock down ATF3 expression." (PMID 39996726, 2025). "Similar cardiac contractile function improvements were observed in ATF3 transgenic mice following injections of serum derived from tumor-bearing mice." (PMID 41322654, 2025). "Oil Red O staining of tumor tissues revealed a significant increase in lipid deposition in the ATF3-knockdown group compared to controls." (PMID 39996726, 2025). "Mechanistically, we show that FADS1 downregulation results in inhibition of tumor growth through induction of ATF3-mediated ER stress response." (PMID 38586033, 2024). "It was reported that ATF3 had prognostic significance as a novel tumor suppressor in ESCC, and it can inhibit ESCC through downregulation of ID1." (PMID 39256364, 2024). "The ATF3 gene is overexpressed in cancer cells, and ATF3 overexpression enhances tumor motility and invasiveness." (PMID 38957318, 2024). "The anti-tumor effect of AETC is associated with the upregulation and downregulation of ATF3 expression, involving inhibiting the Hippo pathway and reducing YAP degradation." (PMID 38474640, 2024). "Research has found that ATF3 regulates transcription by binding to the promoter sequences of multiple oncogenes and tumor suppressor genes, exerting anti-tumor effects." (PMID 38244591, 2024). "In MI and LV hypertrophy in ATF3-transgenic mice models with tumors, an enhancement in tumor growth and an increase in cardiac expression of SerpinA3 were observed." (PMID 38279150, 2024). "An ATF3-transgenic mouse model that had enhanced tumor growth was also shown to have increased levels of expression of SerpinA3 in cardiac tissues but not in tumor cells." (PMID 38279150, 2024). "Another study reported that ASBEL is capable of promoting tumor formation by inhibiting ATF3 through interaction with TCF3." (PMID 39439418, 2024). "The anti-tumor activity of ATF3 has been established in glioblastoma, bladder, lung, colon, and cervical cancer." (PMID 39085957, 2024). "Research on PCa has revealed that sustained SUMOylation of ATF3 can activate the cell cycle and promote tumor proliferation, while SUMOylated flotillin-1 can undergo nuclear translocation to promote epithelial–mesenchymal transition (EMT) transformation." (PMID 39623295, 2024). "To examine how tumor growth affects cardiac dysfunction, we used an ATF3 transgenic mouse model expressing the transcription factor ATF3 under the control of a tetracycline promoter." (PMID 37759510, 2023). "The ATF3-positive area of tumor sections in the two effervescent CBD-SD@DMNs was significantly lower than that in the CBD-SD@DMNs group." (PMID 37198657, 2023). "On the other hand, ATF3, BHLHE40, ZNF263, and FOXP2 transcription factors were strongly associated with GADD45B-low tumor cells." (PMID 37608794, 2023). "Together, our results indicate that Fn invades tumor cells and then releases Fn-Dps to enter the nucleus and bind to ATF3 to promote PD-L1 mRNA transcription." (PMID 37723150, 2023). "One of these targets, ATF3, is a common stress response gene that is up-regulated in response to numerous cellular and environmental insults, many of which occur during tumor development and progression." (PMID 37104245, 2023). "CsA treatment led to ATF3 upregulation and suppression of cancer cell senescence, both in human skin explants and tumor xenografts, which was reversed through ATF3 knockdown." (PMID 37887285, 2023).